ARG1 (arginase 1)
Diseases named in the same sentence as ARG1 in open-access papers (continued):
Sharing a sentence is not in itself a finding about the gene and the disease.
tumor (continued). "CM from LDHA-inhibited (genetically and pharmacologically) CT2A and GL261 cells impaired the expression of a pro-tumor macrophage marker arginase 1 (Arg1) and the percentage of pro-tumor CD68+CD206+ cells in Raw264.7 macrophages." (PMID 38443336, 2024). "The results of the qRT‐PCR experiment revealed a decrease in the relative expression levels of M2 macrophage marker genes MCR1 and ARG1 in the tumor tissue of MS4A4A−/− mice compared to the WT group." (PMID 38997808, 2024). "In that study, paired comparison of tumour and spleen M-MDSCs isolated from CRC mice demonstrated that tumour M-MDSCs expressed higher levels of Arg1 than spleen M-MDSCs." (PMID 38464388, 2024). "Blocking arginase activity mitigated Arg-1-driven tumour progression, providing a potential therapeutic target." (PMID 38592313, 2024). "ARG1 has been shown to inhibit T cell proliferation by depleting l-arginine, an essential amino acid for T cell function, in the tumor microenvironment." (PMID 38422022, 2024). "In contrast, CD8+ Arg1‐specific T cells can specifically affect TME through targeting and reducing Arg1‐expressing tumour cells together with regulatory myeloid lineages." (PMID 38935536, 2024). "Most arginase-1-positive cells appeared sporadically around the edges of tumor tissues to trigger tumor growth and some regions between adipose and tumor tissues." (PMID 38999849, 2024). "As injected LLC cells have similar genetic make-up, the detected difference in the tumor infiltration by ARG1+, F4/80+, and F4/80+/ARG1+ M2-like macrophages in FIH+/+ vs. FIH+/Δ1-2 mice reflects the interactions between the tumor cells and the TME." (PMID 38422022, 2024). "It is consistent with the findings of another study that showed that high Arg-1 expression in primary tumours and increased activity in plasma correlated with a worse prognosis." (PMID 38592313, 2024). "Gene expressions for tumor promoting genes such as Arg1, Il6, Il10, Mmp9, Lgals9, and Vegfa were significantly decreased, whereas that of the tumor suppressive gene such as Il12 increased." (PMID 39702544, 2024). "The core mechanism of arginine deprivation therapy revolves around arginine deiminase (ADI) and arginase (Arg1), which work through different mechanisms to deplete arginine in the tumor microenvironment." (PMID 39239650, 2024). "Slit2 treatment further induced gene expression associated with a tumor-promoting macrophage phenotype by activating MMP-9, VEGF-a, Mrc1, Ccl19, TGF-β1, IL-10, Cd209a, and Arg1." (PMID 39456164, 2024). "In contrast, interstitial MΦs of tumours treated with either RMC-4998 or RMC-4550 had reduced ARG1 expression, suggesting that cancer-cell MAPK pathway inhibition hindered immunosuppressive properties of interstitial MΦs." (PMID 39322643, 2024). "Here we report that DDR2 regulates collagen protein production by CAFs in the tumor microenvironment by controlling the transcription of arginase-1." (PMID 37996700, 2024). "In certain disease states, arginase-1 is released extracellularly, including cancer, where solid tumor-infiltrating neutrophils have decreased intracellular arginase-1, suggesting that it has been released into the tumor microenvironment." (PMID 39253969, 2024). "The finding that Arg1 was one of the top 9 up-regulated genes induced by LPS in FIHΔ1-2/Δ1-2 BMDMs is important, since elevated ARG1 is often used as a marker of tumor promoting macrophages." (PMID 38422022, 2024). "In NSCLC patients, the ARG1+ neutrophil population increased with tumor stage and inversely correlated with the cytotoxic T-cell abundance." (PMID 39061147, 2024). "Tumor-derived extracellular vesicles (EVs) containing miR4458H promote M2-like polarization of TAMs by upregulating arginase-1 (Arg1) expression." (PMID 39450177, 2024).
tumor (continued). "The qPCR analysis (n = 66) revealed an elevated expression of RUNX1 in tumor tissues (P < 0.0001), and the positive associations between RUNX1 mRNA and CD163 mRNA, Arg1 mRNA, CD68 mRNA, CD206 mRNA, IL-10 mRNA were observed (all P < 0.05)." (PMID 38419056, 2024). "Addition of cabozantinib to anti-HER2 treatment enhanced IFNγ levels and reduced tumour growth via inhibition of Arg1+ MDSCs." (PMID 38464388, 2024). "Mechanistically, FFAR2 deficiency in MDSCs significantly reduced the expression of Arg1 through Gαq/Calcium/PPAR-γ axis, which eliminated T cell dysfunction through relieving L-Arginine consumption in tumor microenvironment." (PMID 38402237, 2024). "IL-6 and IL-8 stimulate the production and subsequent secretion of ARG1 from MDSCs by stimulating the PI3K-AKT pathway, causing the suppression of T cells, which contributes to tumor development." (PMID 39337272, 2024). "The high expression of Arginase 1 (Arg1) in M2 macrophages has been shown to mediate polyamine synthesis and collagen formation, as well as to stimulate tumor cell growth and repair damaged tissue." (PMID 39175095, 2024). "KFC-KO tumors showed an increase in F4/80 staining myeloid cells with enhanced staining for Arginase 1, consistent with the presence of tumor-supportive macrophages." (PMID 39636862, 2024). "This study highlights the crucial role of CPT1A-mediated MDSC ferroptosis resistance through SLC7A11 metabolic reprogramming and MDSCs’ immunosuppressive function via the ARG1 signaling pathway in persisting tumor immune evasion." (PMID 39596904, 2024). "ARG1 was upregulated by tumor-CM, whereas HES1 knockdown by siRNA resulted in reduced ARG1 expression." (PMID 39702544, 2024). "Next, we performed multiplex immunohistochemistry analysis on ID8TB−/− tumors from WT and Ddr2−/− mice for expression of Arg1 and various tumor stromal cell type markers (CAF – PDGFRα; macrophage – F4/80)." (PMID 37996700, 2024). "Patients with low tumor Arg-1 expression but high plasma Arg-1 levels exhibited nodal metastases and recurrence, attributed to Arg-1-carrying exosomes detected in all HNSCC patients." (PMID 39409917, 2024). "Immunosuppressive molecules produced by these cells include nitric oxide (NO), Arg-1, and reactive oxygen species (ROS), which induce T lymphocyte anergy, consequently promoting tumor survival and proliferation." (PMID 39457693, 2024). "Beyond immune checkpoint modulation, TAMs orchestrate metabolic subversion through arginase-1 activity, depleting essential amino acids like L-arginine from the tumor microenvironment." (PMID 39450177, 2024). "Tumor-activated neutrophils release arginase 1 (ARG1), reducing L-arginine levels and impacting T cell function." (PMID 38760815, 2024). "As evidence suggests, Arg1 facilitates the conversion of arginine into ornithine and urea, substances known to promote tumor growth, while concurrently curtailing the synthesis of tumoricidal NO." (PMID 38185636, 2024). "Consistent with the presence of liver injury before metastatic engraftment, high Arg1 expression was found in MoM populations isolated from pre-metastatic livers of mice with orthotopically implanted tumor." (PMID 38355776, 2024). "Increased ARG1 expression has been found in many tumours, e.g., hepatocellular carcinoma, non-small cell lung cancer, and carcinoma of the large bowel." (PMID 38920685, 2024). "Depletion of arginine by MDSC Arg1, therefore, indirectly inhibits T cell and NK cell intratumoural number and function thereby suppressing anti-tumour immunity." (PMID 38464388, 2024). "The most well-known pathway for Arg1 induction is through IL-4-STAzzT6, an anti-inflammatory and tumor-supportive signaling pathway." (PMID 38422022, 2024). "In tumor patients, MDSCs have been found to deliver ARG1 to the extracellular environment to promote extracellular L-arginine depletion." (PMID 38609997, 2024).
tumor (continued). "It was documented that co-administration of ARG1 vaccine with anti-PD-1 antibodies created a pro-inflammatory microenvironment and changed the M1/M2 macrophage ratio in the tumor, reducing tumor suppressive immunity." (PMID 39337272, 2024). "During the transformation of normal pancreatic tissues into tumors, potential anti-tumor MHC-II+ macrophages decrease and even disappear, whereas tumor-promoting Arg-1+ macrophages are substantially increased." (PMID 40458305, 2024). "Our results indicated that THP-1 (Mφ) cells treated with tumor-derived exosomes showed significantly increased M2-related proteins including ARG1, TGF-β, PDL1, and CD206." (PMID 39518984, 2024). "Combination treatment using anti-CD3 and anti-HER2 bispecific antibody together with EGFR inhibitor reduced MDSC Arg1 expression, leading to increased levels of Th1 cytokine-mediated anti-tumour immunity." (PMID 38464388, 2024). "In the CT26 mouse model of CRC, immune checkpoint inhibition via anti-CTLA-4 increased Arg1 expression in the tumour microenvironment." (PMID 38464388, 2024). "We observed a significant increase in HES1 expression, in parallel with that of pro-tumor macrophage markers, including ARG1, CD206, PD-L1, and Notch signaling-related proteins." (PMID 39702544, 2024). "Analyzing TAM sorted via flow cytometry and assessing M2 markers (CD163, CD206, Arginase-1) through Western blot, we observed increased tumor volume and M2 marker expression in the SHP2-inhibited group." (PMID 38747738, 2024). "Arginase inhibitors, which do not hinder T-cell proliferation, enhance anti-tumor responses by targeting the arginase enzymes ARG1/2 within the tumor microenvironment (TME)." (PMID 39239650, 2024). "Cancer-produced C5a is a potent neutrophil attractant and contributes to an immunosuppressive tumor environment by upregulating molecules like ARG1, CTLA4, and PD-L1." (PMID 38760815, 2024). "For example, M2 macrophages produce arginase-1 (Arg1), which inhibits M1 macrophage activity and promotes tumor immune evasion." (PMID 39684424, 2024). "Previous studies have found that TAMs upregulate expression of arginase-1 in response to pro-tumor stimuli and depletion of arginase-1 enhances the activity of T cells and promotes tumor regression." (PMID 39702544, 2024). "In conclusion, the current study demonstrates how low expression of the immune marker ARG1 and high expression of the tumour markers CDKN2A and KRT7 correlate with the group of high oncogenic potential HPV and the development of high-grade CIN." (PMID 39712018, 2024). "Myeloid-derived suppressor cells (MDSCs) express arginase-1 highly and are recruited to tumor tissues." (PMID 38999849, 2024). "There was a weakly significant correlation (r = 0.41, p = 0.025) between Arg-1 H scores in the tumor parenchyma and stroma." (PMID 38001706, 2023). "Currently, there is a lack of relevant research on the effects of nitrogen oxides on Arg-1, but it has been shown that nitric oxide can affect liver cell differentiation by affecting the tumor microenvironment." (PMID 37575092, 2023). "In this tumor type, TEVs carried arginase-1 (ARG1), an immunosuppressive molecule present in the tumor microenvironment that leads not only to the depletion of ʟ-arginine, a nutrient required for T-cell expansion but also to proper antigen presentation by DCs." (PMID 36949244, 2023). "Immunostaining of 31 tumor specimens (cohort 1) indicated that Arg-1 was expressed in tumor tissues (parenchyma and stroma) at variable levels, as indicated by the H scores." (PMID 38001706, 2023). "High tumor Arg-1 expression correlated with favorable clinicopathology and longer recurrence-free survival (RFS), while high plasma Arg-1 levels were associated with unfavorable clinicopathology." (PMID 38001706, 2023). "TAM-derived soluble molecules such as IL-10, IL-23, TGF-β, IDO, PGE2, and arginase 1 (ARG1) directly suppress the functions of tumor-infiltrating T and NK cells." (PMID 38008741, 2023).
tumor (continued). "Recently, we revealed that ARG1 was activated in murine bone marrow-derived dendritic cells and human monocyte-derived dendritic cells to suppress the induction of anti-tumor effector T cells in an IL-6-dependent manner." (PMID 36639644, 2023). "We found increased expression of Arginase 1 (Arg1) in monocytes and macrophages in mice injected with ENPP1WT-OE 4T1 cells, which is associated with pro-tumor myeloid-derived suppressor cells (MDSCs) and M2-like macrophages, respectively." (PMID 38117852, 2023). "Increased consumption of L-arginine by ARG1 is one of the known immunosuppressive mechanisms set in place by MDSCs to enhance tumour-immune escape." (PMID 36161514, 2023). "In contrast, 60% of myeloid cells in 66cl4 tumours and less than 2% in 67NR tumours expressed high levels of ARG1, indicating that myeloid cells are the main source of ARG1 in metastatic tumours." (PMID 37980483, 2023). "According to observations in a mouse model, the ARG1 pathway promotes proliferation and tissue repair while supporting tumor growth." (PMID 37046826, 2023). "In turn, high expression of arginase-1 (ARG-1) and IL-10 in tumor-associated neutrophils can trigger Treg cell expansion and T cell exhaustion." (PMID 37370686, 2023). "CCL2, ARG1, ARG2, NOS2, and CCL5 are well-known N2-associated cytokines that promote tumor growth, invasion, and immune suppression." (PMID 37174093, 2023). "IDC fibroblasts significantly enhanced tumor angiogenesis and increased the levels of arginase-1+ cells compared to DCIS fibroblasts, normal fibroblasts and DCIS.com tumor cells grafted alone." (PMID 37091166, 2023). "Immunohistochemically, the tumor cells are positive for hepatocellular markers, such as Hep Par-1, arginase-1, and albumin mRNA in situ hybridization." (PMID 37761023, 2023). "Our results suggest that once Ly6G intermediate cells are released from the bone marrow or spleen, they rapidly migrate to the tumour where ARG1 expression is induced." (PMID 37980483, 2023). "As expected, CD68, CD86, CD206, and Arg-1 levels were more significant in tumor tissues than in ANT." (PMID 38264642, 2023). "For example, TAM production of arginase 1 (Arg-1) leads to the depletion of L-arginine in turn leading to dysfunction of tumor infiltrating lymphocytes by TCR ζ chain downregulation." (PMID 37114134, 2023). "We investigated Arg-1 levels in tumor tissue and the circulation (plasma, exosomes) of HNSCC patients in relation to clinical data." (PMID 38001706, 2023). "CB-1158 is more likely to inhibit cytoplasmic or extracellular ARG1 in plasma, tumours, and inflamed tissues." (PMID 37723490, 2023). "(A) Representative images (left) and immunohistochemical (IHC) score (right) of IHC staining for F4/80 and ARG1 in an orthotopic mPDAC1-TIFM tumor (n = 5) and in healthy murine pancreas (n = 5)." (PMID 37254839, 2023). "The M2/M1-modulating role of ADNVs was further confirmed by immunofluorescence (IF) staining of iNOS (M1) and ARG1 (M2) at tumor tissues." (PMID 36879291, 2023). "MDSCs in the tumor microenvironment express high levels of arginase-1, which decreases arginine levels and inhibits the T cell response." (PMID 36765611, 2023). "In the present study, we found STAP increased ARG1 expression level, which is a poor prognostic factor in tumours." (PMID 37462801, 2023). "Our data confirmed higher Arg1 expression in the splenic M-MDSC from tumor-bearing mice compared to naive mice." (PMID 37149684, 2023). "Of these, we selected the three genes with the highest transcript levels in 66cl4 CD45+ compared with CD45+ from 67NR tumours: Arg1, Fn1 and Thbs1." (PMID 37980483, 2023). "Tumor cells also induce immunosuppression by upregulating arginase 1 (ARG1) and inducible nitric oxide synthase (iNOS) in the MDSCs." (PMID 37711747, 2023). "This is in line with extensive evidence showing that intra-tumoral ARG1 expression can be induced by tumour secretome especially; cytokines, growth factors, and hypoxia." (PMID 37980483, 2023).
tumor (continued). "Checkpoint receptors on T and natural killer (NK) cells, including CTLA-4 and LAG-3, were highly expressed even in tumor-adjacent and normal tissues of liver, coincident with higher levels of B7-H3 and ARG1." (PMID 37768208, 2023). "CBP/EP300-BRD inhibition redirects tumour-associated MDSCs from a suppressive to an inflammatory phenotype through STAT pathway-related gene downregulation and ARG1 and iNOS inhibition, thus limiting tumour growth in a model of colon carcinoma." (PMID 36161514, 2023). "The authors observed an upregulated mRNA expression of Arg1 and Cox‐2 in TAMs together with a low iNOS level, favoring both angiogenesis and tumor growth in a murine model." (PMID 37347290, 2023). "Further analyses revealed that the enhanced leukocyte infiltrate of ITGB4 KD tumor nodules was characterized by arginase-1- and myeloperoxidase-positive cells." (PMID 36932441, 2023). "In contrast, 40–60% of Ly6G+ intermediate cells and 5–11% of Ly6G− and Ly6G+ high cells were positive for ARG1 in 66cl4 tumours, suggesting that ARG1 is a marker for a subpopulation of myeloid cells with intermediate Ly6G expression." (PMID 37980483, 2023). "Proline and polyamides are produced by urea cycle enzyme arginase-1 (ARG1), which is essential for tumor cell growth." (PMID 36733434, 2023). "M2-like macrophages produce ARG1 and other anti-inflammatory factors to promote tumor, while M1-like macrophages produce TNF-α and other pro-inflammatory factors to inhibit tumor." (PMID 38012650, 2023). "Arg1 is normally expressed by hepatocytes, but it is also expressed in TAMs in a variety of tumor types." (PMID 36727849, 2023). "M2-like macrophages increase the expression of arginase 1 (Arg1) and promote arginine metabolism, finally inhibiting immunity and promoting tumor development." (PMID 38264667, 2023). "Externally introduced arginase analogs can inhibit T cells’ antitumor activity by reducing the arginine level in the tumor microenvironment, just as the tumor or immunosuppressive cells expressing arginase 1 can." (PMID 37699892, 2023). "NLRs activation enables MDSCs recruitment and subsequent accumulate to the peritoneal cavity as well as increases Arg-1 expression for immunosuppressive functions, thereby driving tumor progression." (PMID 37217620, 2023). "In summary, DCIS fibroblasts and IDC fibroblasts enhance recruitment of arginase-1+ cells and exert different effects on tumor angiogenesis." (PMID 37091166, 2023). "In tumor, the MDSCs metabolic reprogramming enhances the immunosuppressive activity of Arg1 and iNOS, which will lead to apoptosis of effector T cells and suppression of cell proliferation, and promote tumor proliferation and metastasis." (PMID 37350962, 2023). "The supernatant from the untreated tumor cells significantly induced the expression of the M2 macrophage‐related marker arginase 1 (Arg1) and inhibited that of the M1 macrophage‐related marker inducible nitric‐oxide synthase (iNOS) (second row)." (PMID 37249285, 2023). "Women with ARG1-positive tumours had a significantly lower estimated survival time from diagnosis than women with ARG1-negative tumours." (PMID 37980483, 2023). "Taking these results into account, we ascertain ARG1 is expressed by a heterogenous group of myeloid cells in metastatic 66cl4 tumours." (PMID 37980483, 2023). "The ARG1 protein-positive cells infiltrating the 66cl4 tumour were relatively large and displayed an elongated or stellate shape with long cytoplasmic extensions." (PMID 37980483, 2023). "Arginase1 (ARG1), a representative marker of M2-like macrophages, has been shown to inhibit T cell immune response and accelerate tumor growth." (PMID 38012650, 2023). "Of the 33 ARG1-positive tumours, 2/33 (6%) were grade 1, 12/33 (36%) were grade 2, and 19/33 (58%) were grade 3 (p = 0.005)." (PMID 37980483, 2023). "The tumor cells are positive for markers of hepatocytic differentiation, such as Hep Par-1 and arginase-1." (PMID 37761023, 2023).